IGF1 (insulin like growth factor 1)
Diseases named in the same sentence as IGF1 in open-access papers (continued):
Sharing a sentence is not in itself a finding about the gene and the disease.
breast cancer (continued). "Nimbolide, another neem limonoid was demonstrated to inhibit angiogenesis in breast cancer cells as well as in a xenografted nude mouse model of breast cancer by AR inhibition with the consequent abrogation of the insulin-like growth factor-1 (IGF-1)/PI3K/Akt and HIF-1α/VEGF signaling." (PMID 39055885, 2024). "In addition, CAF-derived IGF-1 stimulates tumour cell invasion and lung metastasis in orthotopic models of breast cancer through activation of the RhoA/ROCK/p-MLC pathway and TAM-derived IGFs promotes cancer cell-stemness and invasiveness in in vitro models of thyroid cancer." (PMID 39165364, 2024). "Thus, a decrease in IGF-1 from adipocytes mediated by 1,25(OH)2D treatment may play a role in decreasing breast cancer cell migration." (PMID 39339753, 2024). "Resveratrol could inhibit IGF-1-mediated cell migration of breast cancer MDA-MB 435 cells in vitro." (PMID 37296375, 2023). "Hence, the impact of genetic variation in IGF1 on IGF1 levels does not appear to substantially modify breast cancer risk." (PMID 37834331, 2023). "Furthermore, the well-known protective role of tamoxifene in breast cancer might also involve a drop in tissue IGF1 through the inhibition of ER." (PMID 37373068, 2023). "Moreover, PA increases insulin sensitivity by reducing Insulin Growth Factor 1 (IGF-1) and inflammation, which may help to protect against breast cancer." (PMID 36980159, 2023). "The prohibitive effects of CR on breast cancer growth may result from the lowering effects of CR on bioavailable levels of insulin, IGF1, leptin and pro-inflammatory molecules; thus, CR impacts molecular pathways leading to the suppression of cell growth and angiogenesis." (PMID 37686596, 2023). "We hypothesized that the direct association between IGF-1 and breast cancer mortality was mainly due to the increased incidence, as it did not influence the transition from breast cancer incidence to mortality." (PMID 38000092, 2023). "Higher plasma levels of insulin-like growth factor-1 (IGF-1) may increase the risk of breast cancer, but, again, the evidence is not clear-cut." (PMID 34406178, 2022). "Thus, we speculate that increased expression of GASP1 may decrease the response of breast cancer cells to paclitaxel by activating the IGF1/IGF1R-related pathways." (PMID 36042202, 2022). "Therefore, ANGPTL-4 and IGF-1 expressions are common in young breast carcinoma tissue." (PMID 35366286, 2022). "In summary, we found a positive association of breast cancer risk with testosterone in post-menopausal women; an inverse association of risk with SHBG in post-menopausal women; and a positive association of risk with IGF-1 in both pre- and post-menopausal women." (PMID 33864017, 2021). "The lack of a significant association between IGF1 and breast cancer-specific mortality may be mainly due to the relatively low number of breast cancer-specific mortality, which could limit the ability to detect a statistically significant association." (PMID 32974138, 2020). "Notably, the study on breast cancer cells found that stimulation of KCC4 mRNA levels by insulin-like growth factor-1 (IGF-1), another serum growth factor, was inhibited by 65% with an inhibitor of ERK1/2, PD98059, but was insensitive to the p38 MAPK inhibitor, SB202190." (PMID 33066544, 2020). "To identify lncRNAs regulated by IGF1 signaling that may be critical for proliferation of breast cancer cells, we examined the transcriptional response induced by the addition of IGF1 to serum starved MCF7 cells after 3 and 8 hrs using whole transcriptome RNAseq." (PMID 32444795, 2020). "In breast cancer, IGF‐1 could induce proliferation and migration, hence high expression of IGF‐1 was related to increased risk of breast cancer, and IGF‐1 was regarded as a promising therapy target in breast cancer." (PMID 32548873, 2020).
breast cancer (continued). "Hence, lncRNA NR2F1‐AS1 induced IGF‐1 in breast cancer cells could activate the phosphorylation of IGF‐1R in HUVECs, which then took effects on angiogenesis." (PMID 32548873, 2020). "Moreover, hyperinsulinemia may also accelerate the progression of breast cancer by stimulation of hepatic IGF-1 synthesis and inhibition the hepatic expression of IGF-1 receptors, leading to an increased circulating IGF-1 level." (PMID 32015762, 2020). "In this report, we aimed to further understand the molecular mechanisms of the biological functions of IGF1 and to leverage the extensive knowledge of IGF1 as a model system to identify and characterize growth factor regulated lncRNAs that are functionally critical in breast cancer." (PMID 32444795, 2020). "Also, higher leptin/adiponectin ratio may induce breast cancer growth, as well as hyperinsulinemia and elevated levels of insulin-like growth factor 1 (IGF-1)." (PMID 31720917, 2020). "Hence, lncRNA NR2F1‐AS1 might promote breast cancer angiogenesis through inducing IGF‐1 expression by sponging miRNA‐338‐3p." (PMID 32548873, 2020). "Hence, lncRNA NR2F1‐AS1 could promote breast cancer angiogenesis via IGF‐1/IGF‐1R/ERK pathway through sponging miRNA‐338‐3p." (PMID 32548873, 2020). "The activated IGF-1 pathway may stimulate the carcinogenesis and progression of breast cancer." (PMID 32015762, 2020). "Thus, lncRNA NR2F1‐AS1 might promote breast cancer angiogenesis through activating IGF‐1/IGF‐1R/ERK pathway." (PMID 32548873, 2020). "However, adipose tissue-derived cells may also be a source for tumor stroma, and their secreted growth factors, especially IGF1, contribute to the growth of breast cancer cells." (PMID 32133294, 2020). "In addition to hormone-dependent prostate and breast carcinomas, the role of IGF1 as a risk factor was evaluated in various non-hormone-dependent malignancies." (PMID 33182502, 2020). "However, while IGF-1 abundance is reported to correlate with both, breast cancer cell proliferation and metastatic potential, TGFβ1 is thought to promote primarily ECM and niche formation, cytoskeletal reorganization, cell motility, and invasion, but not cell proliferation." (PMID 30805306, 2019). "Insulin, insulin-like growth factor-1 (IGF1), leptin, adiponectin, steroid hormones, and cytokines are some host factors associated with obesity that not only influences the initiation and progression of breast cancer, but also affects its response to therapies." (PMID 31121868, 2019). "Thus, mechanisms to link obesity with breast cancer, especially altered estrogen and Insulin-like growth factor 1 (IGF-1) signaling, could drive overall less aggressive tumors with a distinct molecular profile." (PMID 29855282, 2018). "We hypothesize that coffee may play a role for breast cancer prognosis through modulation of tumor IGF1R protein expression in human breast cancer, and that the impact of coffee may be modified by BMI given that both coffee and BMI influence circulating IGF-1 levels in women." (PMID 29928262, 2018). "This extensive network of interactions between IGF1, ER, and HER2 signaling pathways, and potential heterogeneity of risk by tumor subtype for IGF1 genes observed in our study suggest greater complexities in the relationship between IGF1 pathway genes and breast cancer etiology." (PMID 27376028, 2016). "In addition, various exogenous hormones such as insulin-like growth factor 1 (IGF-1) are present in milk, which was suggested as a possible promotional effect for milk as a risk of hormone-dependent cancer, such as breast cancer in women and prostate cancer in men." (PMID 27249558, 2016). "While reduced SHBG increases the fraction of bioavailable estradiol and testosterone, increasing risk for hormone-responsive tumors; elevated IGF-1 could stimulate the growth of breast cancer cells in absence of ER or PR activation." (PMID 26352264, 2015).
breast cancer (continued). "Therefore, it is important to probe the relationship between diabetes mellitus and breast cancer The epidemiological studies have reported that the insulin-like growth factor 1 evokes the growth of colon tumour, suggesting the tumour growth is associated with the levels of insulin." (PMID 25806358, 2015). "Hence, Cyr61 expression may be a key molecule, mediated through IGF-1, which contributes to drug resistance and the aggressive breast cancer phenotype." (PMID 25062088, 2014). "Additionally, Notch activation could enhance the oncogenic potential of other molecules with an important role in obesity and breast cancer angiogenesis, i.e., insulin and IGF-1." (PMID 24202338, 2013). "However, it should be noted that no significant overall associations were found between breast cancer and common germline variation in IGF1 and other genes involved in IGF-1 metabolism in a large, comprehensive study." (PMID 23525758, 2013). "However, IGF-1 may be more important for hormonally independent breast cancers, since a blocking antibody to the IGF-1R in MCF-7 cells does not impede growth whereas this same antibody induces growth retardation in the ER- cell line MDA-MB-231." (PMID 22852056, 2012). "This discrepancy could be the result of the activation of other ER-independent estrogen-related signaling pathways in these breast cancer cells, such as insulin-like growth factor 1 (IGF-1)- or vascular endothelial growth factor (VEGF)-mediated signaling cascades." (PMID 23342282, 2012). "More recently, insulin and IGF-1 have been demonstrated to induce the expression of the zinc transporter LIV-1 in ER positive breast cancer cells and the regulation of this zinc transporter may be important for invasiveness and estrogen-independent cell growth." (PMID 22852056, 2012). "We recently reported that increased birthweight and decreased body size in youth and adolescence were associated with higher IGF-1 and IGFBP-3 levels in adulthood, suggesting that early life body size may act on breast cancer risk through its influence on hormone levels in adulthood." (PMID 22894543, 2012). "Furthermore, exogenous IGF-1 partially reversed the mammary tumor inhibitory effects of 30% CR." (PMID 23342276, 2012). "Although more studies are needed, it is possible that that IGF-1 and/or c-peptide, though not strongly associated with breast cancer risk individually, may be associated with a higher risk when considered in combination with other hormones." (PMID 22017816, 2011). "However, IGF-1 failed to increase the level of Brk phosphorylation or activate Brk kinase activity in T47D breast cancer cells; IGF-1 effects may have gone undetected due to high basal Brk activity in these cells." (PMID 20687930, 2010). "The association of IGF1 with breast-cancer risk was not altered by adjusting for age at menarche, parity, age at first full-term pregnancy, use of exogenous hormones, and BMI, suggesting that the relationship of IGF1 with breast-cancer risk is not confounded by these other risk factors." (PMID 20472501, 2010). "Given the reduced expression of IGFBP3 in the C3.6 cells, IGFBP3's reported role in regulating IGF activity and the reported aberrant regulation of the IGF system in breast cancer, we wanted to further examine if IGF1-induced signalling might be affected by ErbB2 overexpression in these cells." (PMID 20840765, 2010). "Most prospective studies of IGF1 and breast-cancer risk have also reported on IGFBP3, to explore the hypothesis that women with a high concentration of IGF1 relative to IGFBP3 are at an increased risk of breast cancer." (PMID 20472501, 2010). "In multiple experimental systems including primary mammary tumors, cultured human cells, and Brca1-deficient mice, Shukla and colleagues showed that BRCA1 deficiency resulted in increased expression of IRS1, IGF1R and IGFBP2, and increased levels of serum IGF1." (PMID 19843326, 2009).
breast cancer (continued). "Concentration of these cells in cord blood is strongly positively associated with both cord blood levels of insulin-like growth factor 1 (IGF-1) and birth weight, suggesting that IGF-1 may be an important factor in the intrauterine origin of breast cancer." (PMID 19417744, 2009). "Absence of the common IGF1 19 cytosine-adenine (CA)-repeat allele (IGF1-19/-19) inverts the effect of several non-genetic factors on breast cancer risk but the interaction between IGF1-19/-19 and multiparity on breast cancer risk is unknown." (PMID 17311016, 2007). "Pearson’s correlation analysis suggested a link between CD31/34 and lncRNA NR2F1-AS1 and further proved that lncRNA NR2F1-AS1 activates IGF-1/IGF-1R/ERK pathways that promotes angiogenesis and metastasis using in vitro and in vivo breast cancer models." (PMID 39858015, 2025). "While Klotho inhibited IGF-1 and insulin signaling in certain cells, it enhanced DGD signaling in breast cancer cells." (PMID 40004457, 2025). "In breast cancer CAF cell lines with knockdown of ANXA2 we found that the expression of both SPOCK1 and IGF1 was reduced." (PMID 40837013, 2025). "IGF-1 promotes lipogenesis in rat adipocytes, and induces ACC phosphorylation in human breast cancer cells." (PMID 39433211, 2025). "IGF-1 treatment increases the mitochondrial mass and PGC-1β expression in human breast cancer cells through activation of PI3K." (PMID 39433211, 2025). "Subsequently, we compared the expression levels of SPOCK1 and IGF-1 between parental breast cancer fibroblasts and ANXA2-knockdown breast cancer fibroblasts." (PMID 40837013, 2025). "GH, directly or indirectly via IGF-1, has been shown to increase expression of the ABCB, ABCC, and ABCG subfamilies of ABC transporters in breast cancer, melanoma, ovarian cancer, colorectal cancer, and leukemia." (PMID 40806252, 2025). "These experiments suggest that the co-culture of primary human lung fibroblasts with breast cancer cells leads to a significant and steady increase in gene expression of SPP1, IGF1, POSTN and ACTA2." (PMID 40017592, 2025). "This interaction likely amplifies the proliferative and survival signals mediated by IGF1, contributing to the oncogenic properties of PAPP-A in breast cancer." (PMID 38623138, 2024). "Keywords utilized in the search encompassed “Insulin-like Growth Factor-1 (IGF-1)”, “IGF-1 receptor (IGF-1R)”, “IGF-1 isoforms”, “breast cancer”, “tumorigenesis”, “apoptosis inhibition”, “signal transduction”, “cancer metastasis” and “therapeutic targets”." (PMID 39273251, 2024). "In breast cancer, ASNS is regulated by IGF1/IGF2, affecting amino acid transport, metabolism, protein biosynthesis, and stability." (PMID 38474084, 2024). "The results of the current study confirm that 1,25(OH)2D inhibits the migratory potential of breast cancer cells and that this may be due in part to an indirect mechanism—by altering adipocyte release of chemoattractants, such as leptin, adiponectin, IL-6, and IGF-1." (PMID 39339753, 2024). "It is thought that growth hormones, particularly insulin-like growth factor-1 (IGF-1), which influences promotion of cell proliferation and bone growth, may play a role in determining height (and breast density) in premenopausal women, which in turn increases breast cancer risk." (PMID 39001479, 2024). "First, we show in vivo that CR reduces tumor grow, IGF1 levels, and decreases the transcript and protein levels of IGF1R in mammary tumors." (PMID 37686596, 2023). "IGF-1 binds to its cognate receptor to induce phosphorylation of IRS-1 and triggers a cascade of events that eventually results in breast cancer development, progression, and metastasis." (PMID 37511200, 2023). "Breast cancer cells exposed to the complex showed significantly decreased proliferation in addition to secreting less VEGF-A, TGF-β and IGF-1." (PMID 37593220, 2023).
breast cancer (continued). "The association between IGFBP-3 and breast cancer risk is reportedly due to its interaction with IGF-1, and this interaction can be eliminated by the adjustment of IGF-1, suggesting that IGF-1 itself is an inducing factor of breast cancer." (PMID 36755926, 2023). "Similar to IGF-1, estrogen can also play a role in breast cancer through the MAPK and PI3K/Akt signaling pathways, and estrogen and IGF-1 exhibit crosstalk." (PMID 36755926, 2023). "This study aimed to determine the correlation between CTLA-4 expression in peripheral blood and insulin-like growth factor-1 (IGF-1) serum levels and their impact on trastuzumab responsiveness in HER-2-positive patients with breast cancer." (PMID 38406785, 2023). "Insulin and insulin-like growth factor 1 (IGF1) are metabolic hormones, which are often upregulated to stimulate proliferation in breast cancer." (PMID 38136416, 2023). "In breast cancer cells, 4-OHT suppresses IGF-1 signaling due to the accumulation of extracellular IGFBP1, which is mediated by GPER1 and CREB." (PMID 37907850, 2023). "Uncontrolled stimulation of the present pathway by ER, IGF-1, and HER3 is behind breast cancer advancement and progression." (PMID 37228871, 2023). "Insulin-like growth factor 1 (IGF-1) promotes the proliferation, differentiation, and survival of cells and tissues but also those of various IGF-1-sensitive tumor types, such as breast cancer, rhabdoid tumors, and bone and soft tissue sarcomas." (PMID 36009569, 2022). "In breast cancer, then a downstream molecule of the AKT/mTOR pathway phosphorylates ERα which binds to promoter of target genes, and upregulates IGF-1, IGF-1R." (PMID 35784325, 2022). "IGF1 induces EMT in diverse diseases, such as breast cancer, prostate cancer, and gastric cancer, thereby enhancing the invasion and metastasis of cells." (PMID 35964060, 2022). "Ranking biomarkers in an agnostic manner using MR-BMA reinforced our confidence in the strength of our findings and provided us with information about the importance of testosterone, HDL cholesterol, IGF-1, and ALP in breast cancer liability." (PMID 36424572, 2022). "ASCs/MSCs secrete various growth factors including IGF1 and EGF, and numerous cytokines such as leptin, IL6, adipsin, and TNFα, which stimulate proliferation and survival of breast cancer cells." (PMID 36010901, 2022). "IGF-1 exposure contributed to increases in FASN mRNA and protein expression in both MCF-7 and MDA-MB-231 breast cancer cells." (PMID 36096767, 2022). "The majority of breast cancer metastases are lytic; breast cancer cells produce TNF-A, IL-8, IL-11, IGF1, LIF (leukemia inhibitory factor), lysyl oxidase, RANK ligands, and PTHrP." (PMID 36230523, 2022). "To investigate the role of IGF-1 induced SRSF-1 FASN regulation, we knocked down SRSF-1 by RNAi in breast cancer cells and performed RT-qPCR for FASN mRNA expression." (PMID 36096767, 2022). "Xentuzumab is a humanized, IGF-1 and IGF-2 neutralizing antibody that has been tested in combination with everolimus and exemestane in a phase Ib/II trial of advanced, ER+ breast cancer." (PMID 36046843, 2022). "Upon SRPK2 knockdown and inhibition, we observed a decrease in FASN protein and mRNA stability, respectively, in response to IGF-1 exposure that was specific to triple negative and HER2+ breast cancer cell lines." (PMID 36096767, 2022). "Most existing studies on the effects of exercise on inflammatory factors and IGF systems in breast cancer survivors examine IL-6, IL-10, IL-1β, TNF-α, CRP, IGF-1, and IGFBP-3 levels." (PMID 36482346, 2022). "Related studies have shown that IGF-1 and IGF-2 are highly expressed in a variety of malignant tumors, suggesting that they are closely related to the occurrence and development of breast cancer." (PMID 35845730, 2022). "In breast cancer, in model autoimmune diseases, as in TED, the binding of IGF-1 to IGF-1R triggers the PI3K/AKT/mTOR signaling pathway." (PMID 35784325, 2022).